LEPR (leptin receptor)
Diseases named in the same sentence as LEPR in open-access papers (continued):
Sharing a sentence is not in itself a finding about the gene and the disease.
leiomyoma (2 papers, 2023 to 2025). A well-circumscribed benign smooth muscle neoplasm characterized by the presence of spindle cells with cigar-shaped nuclei, interlacing fascicles, and a whorled pattern. "To do this, we sought to investigate the influence of adipocyte coculture on leptin receptor pathways in human uterine myometrium and leiomyoma cells." (PMID 36771423, 2023). "Additionally, inhibitors of MAPK/ERK, JAK2/STAT3, and PI3k/AKT leptin receptor pathways are more effective in leiomyoma cells cocultured with adipocytes." (PMID 36771423, 2023). "However, some scholars believe that in obese women, hormones secreted by adipocytes or adipocytes may promote the development and growth of leiomyoma by activating leptin receptor signaling pathway." (PMID 40101032, 2025). "The MAPK/ERK is another marker in leptin receptor signaling pathways and it was observed previously that leptin treatment increases MAPK/ERK signaling in immortalized leiomyoma cells." (PMID 36771423, 2023).
male infertility (2 papers, 2013 to 2023). The inability of the male to effect fertilization of an ovum after a specified period of unprotected intercourse. "Through peripheral blood samples for DNA extraction and genotypic analysis, the association between polymorphisms of LEP and LEPR genes and male infertility has been examined." (PMID 37662867, 2023). "The mechanistic basis for the regulatory role of LEP signaling in male infertility, especially between LEPR polymorphisms of spermatozoa and male infertility, awaits further analysis." (PMID 37662867, 2023). "(ii) A novel missense mutation in the LEPR gene (Gln223Arg) with male infertility in a Chinese population is determined by PCR-RFLP technology." (PMID 37662867, 2023). "The present study examined the relationship between allelic and genotypic frequencies of the Gln223Arg polymorphism with male infertility in a Chinese population and analyzed semen variables to determine whether Gln223Arg polymorphism of LEPR was directly associated with male infertility." (PMID 37662867, 2023). "Re-expression of LepR selectively in PMV neurons of LepR null female mice induced pubertal development and improved fertility; but, intriguingly, no amelioration of male infertility was observed." (PMID 22851226, 2013).
metastasis (2 papers, 2020 to 2021). The spread or migration of cancer cells from one part of the body (where they first appeared) to another. "Taken together, our findings support the importance of the leptin/LEPR/KHDRBS1 axis and of adiponectin in the progression of bone metastasis and suggest their potential application in pharmacological interventions." (PMID 33213024, 2020).
Miscarriage (2 papers, 2016 to 2018). A pregnancy that ends at a stage in which the fetus is incapable of surviving on its own, defined as the spontaneous loss of a fetus before the 22th week of pregnancy. "On the other hand, SNPs of leptin and LEPR genes are risk factors for miscarriage." (PMID 29160594, 2018).
myeloma (2 papers, 2016 to 2020). "Our findings are consistent with single cell qRT-PCR analysis of normal MSCs exposed to myeloma cells, which exhibit trends for suppression of LEPR and PPARG." (PMID 33680918, 2020). "Anti-leptin receptor antibody was administrated in co-culture system of NCI-H929 + adipocytes and U266 + adipocytes, and the growth of myeloma cells was suppressed." (PMID 27863383, 2016).
Myocardial fibrosis (2 papers, 2022 to 2023). "Furthermore, SOCS3 ablation in LepR-expressing cells caused an increase in the relative collagen area of the heart in both young adult and middle-aged mice, which indicates the development of myocardial fibrosis." (PMID 35742928, 2022).
oropharyngeal cancer (2 papers, 2019 to 2023). Carcinoma, predominantly squamous cell, arising from the epithelial cells of the oropharynx. "A literature review indicates that genetic variation in LEPR modifies the risk of several tumors, including breast, colorectal, thyroid, and oropharyngeal cancers." (PMID 37892180, 2023). "According to the findings of stratified analysis, we found that LEPR rs1137101 locus might be associated with the susceptibility of oral and oropharyngeal cancer." (PMID 31196966, 2019).
periapical granuloma (2 papers, 2015 to 2022). Chronic nonsuppurative inflammation of periapical tissue resulting from irritation following pulp disease or endodontic treatment. "The presence of leptin and LEPR mRNAs, determined by a quantitative real-time PCR (qRT-PCR), and leptin and LEPR proteins, analyzed by immunoblot, have also been demonstrated in human periapical granulomas." (PMID 35216099, 2022). "Key words:Apical granuloma, dental pulp, endodontics, leptin, leptin receptor, immune system, immunohistochemistry, periapical inflammatory response." (PMID 25662559, 2015). "Further studies are required analyzing the expression of LEPR in periapical granulomas in order to fully elucidate the roles of leptin and LEPR in the physiology of periapical chronic inflammatory response." (PMID 25662559, 2015). "LEPR gene has been detected in experimental rat periapical lesions and, recently, it has been demonstrated that human periapical granulomas express LEPR." (PMID 25662559, 2015). "Leptin receptor (LER) has been identified in human periapical granulomas." (PMID 25662559, 2015).
peritonitis (2 papers, 2011 to 2018). Inflammation of the peritoneum (tissue that lines the abdominal wall and covers most of the organs in the abdomen). "• LEP Gene -2548G > A, and the LEPR Gene 223A > G polymorphisms increase the risk of death in secondary peritonitis with an odds ratio of 4.64 and 3.57, respectively." (PMID 21943151, 2011). "The purpose of this study was to explore the association of genetic polymorphisms of LEP or LEPR with an unfavourable outcome (death) in patients with non-appendicular secondary peritonitis." (PMID 21943151, 2011).
pseudohypoparathyroidism type 1A (2 papers, 2020 to 2024). "The second frequently identified genetic obesity disorders were biallelic LEPR pathogenic variants (6/37), followed by GNAS pathogenic variants leading to pseudohypoparathyroidism type 1a (5/37)." (PMID 32384097, 2020).
respiratory infections (2 papers, 2014 to 2022). "Additionally, LEPR deficient mouse exhibits increased susceptibility to respiratory infections suggesting a leptin requirement in the pulmonary innate and adaptive immune response to infection." (PMID 36589459, 2022).
Sertoli Cell-Only Syndrome (2 papers, 2010 to 2022). A type of male infertility in which no germ cells are visible in any of the biopsied SEMINIFEROUS TUBULES (type I) or in which germ cells are present in a minority of tubules (type II). "In infertile men with obstructive azoospermia, Sertoli cell-only syndrome, and varicocele, leptin receptor expression in Leydig cells is inversely correlated with the serum levels of testosterone." (PMID 35246515, 2022). "In addition, these authors showed that the percentage of Leydig cells expressing leptin receptor increased in Sertoli only cell syndrome when compared to control individuals." (PMID 20178606, 2010).
venous ulcers (2 papers, 2015 to 2017). "Furthermore, we have shown that LEPR is down-regulated in venous ulcers, another type of chronic wound." (PMID 26318001, 2015). "In addition, we have previously shown that LEPR is down-regulated in venous ulcers of non-diabetic patients." (PMID 26318001, 2015).
acute promyelocytic leukemia (1 paper, 2018). An aggressive form of acute myeloid leukemia (AML), characterized by arrest of leukocyte differentiation at the promyelocyte stage, due to a specific chromosomal translocation t(15;17) in myeloid cells. "Primary acute promyelocytic leukemia (APL) cells express high levels of the long isoform of the LEPR." (PMID 30546345, 2018).
adenoma (1 paper, 2024). A neoplasm arising from the epithelium. "Their findings revealed mRNA expression of the full-length LepR and isoforms B219.1 and 3 in each of the investigated ACC and adenomas." (PMID 39201370, 2024).
adrenal tumors (1 paper, 2024). "The study highlights the diagnostic and prognostic significance of leptin receptor isoforms in adrenal tumors." (PMID 39201370, 2024). "The aim of the study was to evaluate the diagnostic and prognostic significance of leptin receptor isoforms in adrenal tumors." (PMID 39201370, 2024). "The literature currently available does not provide any data evaluating the expression patterns of different leptin receptor isoforms in adrenal tumours." (PMID 39201370, 2024). "In conclusion, we have identified distinct patterns of leptin receptor isoform expression in adrenal tumors, underscoring leptin’s significant role in oncogenesis." (PMID 39201370, 2024). "In our investigation, we identified the mRNA expression of various LepR isoforms across all analyzed types of adrenal tumors, providing evidence that supports leptin’s potential involvement in adrenal tumorigenesis." (PMID 39201370, 2024). "Their study aimed to scrutinize potential variations in LepR mRNA expression within human adrenal tumors." (PMID 39201370, 2024). "Our paper is the first to investigate the potential pathological involvement of leptin receptor isoforms in adrenal tumors’ pathogenesis." (PMID 39201370, 2024). "They found that, although the leptin receptor is expressed on both the mRNA and protein level in adrenal tumors, leptin does not regulate the proliferation of neoplasms." (PMID 39201370, 2024).
adrenocortical adenoma (1 paper, 2024). "Expression of LepR v1 was significantly lower in carcinoma tissues compared to adrenocortical adenoma and controls (p = 0.016)." (PMID 39201370, 2024).
Adult onset (1 paper, 2019). Onset of disease manifestations in adulthood, defined here as at the age of 16 years or later. "As a consequence of gene mutation of the leptin receptor, db/db mice exhibit spontaneous glucose metabolic disorder, which is similar to the clinical symptoms of adult-onset T2DM." (PMID 31637120, 2019).
allergic asthma (1 paper, 2013). A asthma with a basis in a pathological type I hypersensitivity reaction. "Further studies are warranted to understand the complex yet critically important relationship between serum/plasma leptin levels, leptin receptor expression, and severity of allergic asthma." (PMID 23383125, 2013).
amyloid (1 paper, 2020). "We postulate that astrocytes may utilize LepR signalling to mediate and drive their metabolically active state when degrading amyloid in the AD brain." (PMID 33218163, 2020).
atrophic gastritis (1 paper, 2016). "This study presents the first evidence supporting the theory that HFD-induced enhanced leptin receptor signaling in the gastric mucosa causes atrophic gastritis in a murine model." (PMID 26839577, 2016). "Our results might therefore directly indicate the involvement of leptin receptor signaling in the initiation of obese-associated gastric atrophy." (PMID 26839577, 2016). "In this study, we show that diet-induced obese WT mice exhibit overexpression of leptin and activation of leptin receptor signaling in the gastric mucosa, leading to atrophic gastritis with intestinal metaplasia of the gastric mucosa." (PMID 26839577, 2016).
Autoimmunity (1 paper, 2022). The occurrence of an immune reaction against the organism's own cells or tissues. "Studies of leptin or leptin receptor deficient mouse models have revealed striking protection from autoimmune development in many models of induced autoimmunity." (PMID 36479348, 2022).
Barrett's oesophagus (1 paper, 2007). "Preliminary data have confirmed the presence of leptin receptor isoforms in Barrett's oesophagus and adenocarcinoma: interestingly expression was reported to increase with progression along the dysplasia-carcinoma sequence." (PMID 17559672, 2007).
bone marrow fibrosis (1 paper, 2023). "Primary myelofibrosis (PMF) is associated with bone marrow fibrosis; mouse models show that transforming growth factor-beta (TGF-β) and platelet-derived growth factors (PDGFs) are involved in fibrosis and that the source of myofibroblasts is CAR/LepR+ cells." (PMID 36805714, 2023).
brain tumor (1 paper, 2019). "The use of antagonists against leptin receptor, leptin, or the signaling pathway (JAK/STAT) may prove promising in the treatment of brain tumor." (PMID 30803210, 2019).
Central hypothyroidism (1 paper, 2021). A type of hypothyroidism due to an insufficient stimulation of an otherwise normal thyroid gland. "It was suggested that the central hypothyroidism phenotype is linked to leptin receptor (LEPR) dysfunction." (PMID 34566885, 2021).
childhood asthma (1 paper, 2018). "We hypothesized that the polymorphism in leptin (LEP) and leptin receptor (LEPR) genes is associated with childhood asthma and may affect their serum level." (PMID 30203371, 2018).
cholelithiasis (1 paper, 2017). The presence of crystallized deposits forming in the gallbladder or biliary tree, primarily composed of cholesterol, bilirubin, and bile. "The changes in the mRNA expression of leptin and leptin receptor within the gallbladder of dogs with cholelithiasis further underline that leptin may be a factor involved in the development of cholelithiasis, considering its important physiological role in gallbladder." (PMID 29088261, 2017). "Leptin and leptin receptor expression was upregulated in the gallbladder tissues of cholelithiasis patients (p < 0.01 and p < 0.001, respectively)." (PMID 29088261, 2017). "We also demonstrated a relative increase in leptin and leptin receptor mRNA expression in the gallbladder tissues of dogs with cholelithiasis compared with that in healthy dogs." (PMID 29088261, 2017).
chronic hepatitis C (1 paper, 2020). "LEPR Gln223Arg GA genotype was represented in 40% of controls, 70% of chronic hepatitis C patients, 40% of NASH patients, 80% of cirrhotic patients and 35% of HCC patients." (PMID 33369452, 2020).
chronic obstructive pulmonary disease (1 paper, 2013). A chronic and progressive lung disorder characterized by the loss of elasticity of the bronchial tree and the air sacs, destruction of the air sacs wall, thickening of the bronchial wall, and mucous accumulation in the bronchial tree. "The interaction between cigarette exposure and leptin receptor has been further addressed in a study of chronic obstructive pulmonary disease, which inferred that underexpression of leptin receptor acted as a predisposing factor to cigarette smoking-induced lung disease." (PMID 23593308, 2013).
Cirrhosis (1 paper, 2017). A chronic disorder of the liver in which liver tissue becomes scarred and is partially replaced by regenerative nodules and fibrotic tissue resulting in loss of liver function. "Analysis of liver tissue samples from HCC patients exhibit somatic mutations in the leptin receptor (LEPR) in the stage of cirrhosis during chronic HCV infection." (PMID 28758929, 2017).
clear cell carcinoma (1 paper, 2017). "This identified adenocarcinoma (HEY3, SKOV3) and teratocarcinoma (PA1) cell lines expressing LEPR, along with adenocarcinoma (A2780) and clear cell carcinoma (ES2) cell lines that did not express detectable LEPR." (PMID 29212170, 2017).
cyst (1 paper, 2023). A sac-like closed membranous structure that may be empty or contain fluid or amorphous material. "Moreover, the expression of LEPR positively correlated with the maximum diameters of tumor and cyst, as well as volumes of tumor and cyst (all r > 0.1 and all p <0.05)." (PMID 37509115, 2023).
diabetic polyneuropathy (1 paper, 2013). "We chose two distinct models to test our hypothesis: 1) the leptin receptor deficient mouse (dbdb) model of diabetic polyneuropathy and 2) superoxide dismutase 1 knockout (Sod1−/−) mouse model of in vivo oxidative stress." (PMID 23750273, 2013). "We chose two distinct models to address the questions, the well-characterized leptin receptor deficient (dbdb) mouse model of diabetic polyneuropathy, and mice lacking the superoxide dismutase 1 (Sod1) gene (Sod1−/−) as a model of in vivo oxidative stress." (PMID 23750273, 2013).
diabetic retinopathy (1 paper, 2018). "However, although leptin receptor-deficient (db/db) mice have been evaluated for diabetic retinopathy, an extensive characterisation of retinal disease in BTBR ob/ob leptin (ligand)-deficient obese mice has not yet been carried out." (PMID 30094465, 2018).
energy metabolism disorder (1 paper, 2022). "Our results further substantiated the nonfunctional role of investigating LEP and LEPR genes as causative in a complex energy metabolism disorder." (PMID 35886710, 2022).
esophageal adenocarcinoma (1 paper, 2012). A malignant tumor with glandular differentiation arising predominantly from Barrett mucosa in the lower third of the esophagus. "Obesity is also associated with upregulated leptin receptor and adiponectin receptor expression in esophageal adenocarcinoma cells." (PMID 23304125, 2012). "Over 90% of esophageal adenocarcinomas were reported to express the leptin receptor, with most (67%) showing markedly upregulated expression." (PMID 23304125, 2012).
esophageal squamous cell carcinoma (1 paper, 2017). Esophageal squamous cell carcinoma (ESCC) is a type of esophageal carcinoma (EC) that can affect any part of the esophagus, but is usually located in the upper or middle third. "In this study, we aimed to examine the association of transcription factor 7-like 2, Leptin (LEP) and LEP receptor (LEPR) polymorphisms with esophageal squamous cell carcinoma (ESCC)." (PMID 29312594, 2017).
G6PD deficiency (1 paper, 2025). An X-linked genetic condition caused by alterations in the gene G6PD that result in moderately to severely decreased activity levels of the enzyme glucose-6-phosphate dehydrogenase. "G6PD deficiency impacts insulin signaling activation, while LEPR and KRAS modulate insulin sensitivity and glucose metabolism." (PMID 39823117, 2025).
galactosaemia (1 paper, 2018). "From our earlier studies, we have suggested that abnormal N-glycosylation could putatively disrupt leptin-HPG signalling resulting from distorted Ob-r, soluble leptin receptor (sOb-R) and GnRH receptor (GnRH-R) function in galactosaemia." (PMID 30231941, 2018).
gastric adenocarcinoma (1 paper, 2019). "Lower LEP occurrence has also been reported with less differentiated gastric adenocarcinomas, and the authors suggested silencing of LEP/LEPR expression in advanced stages of cancers." (PMID 31592340, 2019).
kidney cancer (1 paper, 2020). Primary or metastatic malignant neoplasm involving the kidney. "According to the Kaplan–Meier survival curves, patients with kidney cancer in the low/medium-expression level group for each of LEPR and NEGR1 genes had a long-time life expectancy in comparison to those in the high-expression level group." (PMID 33299884, 2020). "Underexpressed LEPR, NEGR1, TMEM18, and SH2B1 genes prevented the progression and metastasis of kidney cancer." (PMID 33299884, 2020).
left ventricular hypertrophy (1 paper, 2023). Enlargement of the LEFT VENTRICLE of the heart. "Similarly, pressure-mediated left ventricular hypertrophy and mechanical stretch also upregulate leptin receptor gene expression." (PMID 37869164, 2023).
liver cirrhosis (1 paper, 2020). "This study aimed to assess between the level of the LEP hormone and LEPR Gln223Arg in Egyptian patients with liver cirrhosis that leads to HCC." (PMID 33369452, 2020). "This study was conducted to assess between LEPR Gln223Arg and serum LEP level in Egyptian patients with liver cirrhosis that leads to HCC and to clarify its relationship with the clinical-pathological characteristics of patients with HCC." (PMID 33369452, 2020).
liver inflammation (1 paper, 2021). "AP-1, TLR2, and IL1-β, genes that are differentially regulated during the pathological progression of NASH liver inflammation, and SCD1, LEPR, and other genes related to NASH lipid deposition, were regulated by caffeine, but EGCG had no significant regulatory effect." (PMID 34881283, 2021).